IRS2 (insulin receptor substrate 2)
Description:
Signaling adapter protein that participates in the signal transduction from two prominent receptor tyrosine kinases, insulin receptor/INSR and insulin-like growth factor I receptor/IGF1R. Plays therefore an important role in development, growth, glucose homeostasis as well as lipid metabolism. Upon phosphorylation by the insulin receptor, functions as a signaling scaffold that propagates insulin action through binding to SH2 domain-containing proteins including the p85 regulatory subunit of PI3K, NCK1, NCK2, GRB2 or SHP2. Recruitment of GRB2 leads to the activation of the guanine nucleotide exchange factor SOS1 which in turn triggers the Ras/Raf/MEK/MAPK signaling cascade (By similarity). Activation of the PI3K/AKT pathway is responsible for most of insulin metabolic effects in the cell, and the Ras/Raf/MEK/MAPK is involved in the regulation of gene expression and in cooperation with the PI3K pathway regulates cell growth and differentiation. Acts a positive regulator of the Wnt/beta-catenin signaling pathway through suppression of DVL2 autophagy-mediated degradation leading to cell proliferation. Plays a role in cell cycle progression by promoting a robust spindle assembly checkpoint (SAC) during M-phase. In macrophages, IL4-induced tyrosine phosphorylation of IRS2 leads to the recruitment and activation of phosphoinositide 3-kinase (PI3K).
Synonyms: IRS-2
Tractability: Antibody: its Gene Ontology location is reachable by antibodies, with high confidence. PROTAC: UniProt records ubiquitination sites on it; ubiquitination databases record sites on it; its protein half-life has been measured.
Gene: Protein-coding gene on chromosome 13 (109,752,695 to 109,786,583, reverse strand). Ensembl gene ENSG00000185950.
Subcellular location: Cytoplasm, cytosol
Subcellular location (Human Protein Atlas): Cytosol; Aggresome
Pathways (Reactome):
Signal Transduction: Erythropoietin activates Phosphoinositide-3-kinase (PI3K); Erythropoietin activates Phospholipase C gamma (PLCG); Erythropoietin activates RAS; Erythropoietin activates STAT5; IRS activation; IRS-mediated signalling; IRS-related events triggered by IGF1R; PI3K Cascade; PI3K/AKT activation; PI5P, PP2A and IER3 Regulate PI3K/AKT Signaling; PIP3 activates AKT signaling; RAF/MAP kinase cascade; SOS-mediated signalling; Signal attenuation; Signaling by Erythropoietin; Signaling by Leptin
Immune System: Growth hormone receptor signaling; Interleukin-7 signaling
Developmental Biology: RET signaling
Disease: Constitutive Signaling by Aberrant PI3K in Cancer
Gene Ontology:
Molecular function: protein binding; signaling adaptor activity; transmembrane receptor protein tyrosine kinase adaptor activity; 14-3-3 protein binding; insulin receptor binding; phosphatidylinositol 3-kinase activator activity; phosphatidylinositol 3-kinase binding; protein domain specific binding; protein kinase binding; protein phosphatase binding; protein-macromolecule adaptor activity
Biological process: cellular response to insulin stimulus; insulin-like growth factor receptor signaling pathway; negative regulation of long-chain fatty acid import across plasma membrane; positive regulation of D-glucose import; positive regulation of fatty acid beta-oxidation; positive regulation of glucose metabolic process; positive regulation of glycogen biosynthetic process; glucose metabolic process; insulin receptor signaling pathway; lipid homeostasis; negative regulation of B cell apoptotic process; phosphatidylinositol 3-kinase/protein kinase B signal transduction; positive regulation of B cell proliferation; positive regulation of cell population proliferation; positive regulation of insulin secretion; regulation of lipid metabolic process; response to glucose; signal transduction; cell surface receptor protein tyrosine kinase signaling pathway; cellular response to endothelin; cellular response to glucose stimulus; positive regulation of phosphatidylinositol 3-kinase/protein kinase B signal transduction; positive regulation of transport
Cellular component: cytoplasm; cytosol; plasma membrane
Genetic constraint (gnomAD): Loss-of-function variants: 28 observed, 40.83 expected, observed/expected ratio (o/e) 0.69, 90% interval 0.51 to 0.94. The synonymous counts are far from expectation, so gnomAD's model fits this gene poorly and the ratio says little. Missense variants: 2,022 observed, 1,532.8 expected, observed/expected ratio (o/e) 1.32, 90% interval 1.27 to 1.37. Synonymous variants: 1,181 observed, 758.6 expected, observed/expected ratio (o/e) 1.56, 90% interval 1.48 to 1.63.
Homologues: Orthologues: chimpanzee IRS2 (99% identical), macaque IRS2 (98% identical), dog IRS2 (87% identical), rat Irs2 (86% identical), mouse Irs2 (85% identical), pig IRS2 (72% identical), zebrafish irs2b (46% identical), tropical clawed frog IRS2 (43% identical), zebrafish irs2a (42% identical), Drosophila melanogaster chico (17% identical). Paralogues in human: IRS1 (36% identical), IRS4 (24% identical).
Diseases named in the same sentence as IRS2 in open-access papers:
IRS2 is named in the same sentence as 192 diseases in open-access papers, as found by Europe PMC text mining. Sharing a sentence is not in itself a finding about the gene and the disease. The quoted sentences say what the papers report.
Insulin resistance (309 papers, 2007 to 2025). Increased resistance towards insulin, that is, diminished effectiveness of insulin in reducing blood glucose levels. "Among the six mammalian IRS proteins (IRS-1, IRS-2, IRS-3, IRS-4, IRS-5, IRS-6), IRS-1 and IRS-2 are typically considered key nodes in the insulin signaling system, closely associated with the development of insulin resistance." (PMID 39966707, 2025). "Among the four mammalian IRS proteins (IRS-1, IRS-2, IRS-3, IRS-4), IRS-1 and IRS-2 are considered key nodes in the insulin signaling system, and their dysfunction is closely linked to the development of insulin resistance." (PMID 39966707, 2025). "This implicates increased hepatic glucose metabolism in the down-regulation of IRS-2 of hepatic insulin resistance linked to the development of MASLD." (PMID 41196673, 2025). "Expression of hepatic GCK is maintained through regulation by IRS-1 in hyperinsulinemia as insulin resistance develops and decreased suppression by IRS-2-linked FoxO1 signaling." (PMID 41196673, 2025). "To elucidate the underlying mechanism of HB in insulin resistance among obese rats, we examined the protein expression of IRS2/PI3K/AKT." (PMID 39458511, 2024). "Insulin resistance in 7CafD females was associated with a reduced expression of insulin signalling and glucose transport genes in all metabolic tissues: Insr and Irs2 in liver, Insr and Slc2a4 in WAT, and Slc2a4 in muscle." (PMID 39596499, 2024). "IKK and JNK1 phosphorylate IRS1 and IRS2 on the serine residue, which causes activation of the gene linked to insulin resistance and inflammation." (PMID 37241737, 2023). "Conversely, the disruption of IRS-2 adversely affects both peripheral insulin signaling and pancreatic β-cell function, resulting in a gradual decline in glucose homeostasis in IRS-2-deficient mice, primarily attributed to liver insulin resistance." (PMID 37850091, 2023). "Whole-body deletion of insulin receptor substrate–2 (IRS-2) in mice causes a T2D-like syndrome due to reduced β cell function and mass in the face of marked insulin resistance." (PMID 37712417, 2023). "The Gly1057Asp variation of the IRS2 gene has been widely documented, and it is thought to be linked to insulin resistance, T2D, and obesity." (PMID 36589630, 2022). "Obestatin also increases the expression of glucokinase and insulin receptor substrate-2 (IRS-2), which has been implicated in compensatory beta-cell hyperplasia in response to high-fat diet-induced insulin resistance." (PMID 35454106, 2022). "IRS-1 causes insulin resistance, while IRS-2 is needed for hepatic insulin activity, and its increase is related to prediabetes." (PMID 36290594, 2022). "Systemic IRS2-deficient mice exhibit a striking phenotype of insulin resistance, severe diabetes, and juvenile lethality." (PMID 33746806, 2021). "Chronic insulin stimulation degrades insulin receptor substrate 1 and 2 (IRS1 and IRS2) protein and causes insulin resistance in vitro." (PMID 33547878, 2021). "IRS-1- and IRS-2-deficient mice not only exhibited insulin resistance but also diminished eNOS activity." (PMID 34440804, 2021). "Our data confirmed that Irs2 was a key element within the network of molecular mechanisms linked to insulin resistance." (PMID 33348802, 2020). "In the liver being a principal site for IRS2 abnormality, AngII causes hepatic fibrosis to exert insulin resistance." (PMID 33270683, 2020). "In the liver, insulin resistance was also associated with miR-33, which modulates the expression of insulin receptor substrate 2 (IRS2)." (PMID 31404962, 2019). "Using insulin-resistant mice deficient for insulin receptor substrate 2 (Irs2), we highlight dramatic impairment of proregenerative fibroblast growth factor 7 (Fgf7) signaling between stromal niche cells and LPCs during chronic injury." (PMID 30695023, 2019). "The mice deficient in IRS-2 have been shown to display T2DM-like phenotypes due to insulin resistance of the liver and defective pancreatic β-cell function." (PMID 30975165, 2019).
Insulin resistance (continued). "Studies have shown that IRS2 polymorphisms are related to insulin resistance, thus IR-β and IRS2 are useful markers for the detection of insulin resistance." (PMID 29318158, 2017). "IRS2 is a key regulator of hepatic insulin resistance and has been associated with lifespan in mice." (PMID 28351387, 2017). "Loss of IRS-2 function results in hepatic insulin resistance, an important pathophysiological feature of age-related type 2 diabetes." (PMID 28351387, 2017). "Previously, it has been shown that disruption of IRS-2 in mice caused a marked insulin resistance in adipose tissue." (PMID 27066503, 2016). "Loss of IRS-2 causes diabetes in mice due to β-cell insufficiency and peripheral insulin resistance." (PMID 26919700, 2016). "Here, we show that ‘selective insulin resistance' is caused by the differential expression of Irs1 and Irs2 in different zones of the liver." (PMID 27708333, 2016). "The characteristics of insulin resistance differ among organs and tissues; in liver IRS2-mediated pathway is impaired, causing hyperglycemia while IRS1-mediated pathway is preserved to some extent, inducing hyperlipidemia." (PMID 27247938, 2016). "The overactivity of UPS and inappropriate degradation by the UPS of IRS-1 and IRS-2 was associated the development of insulin resistance." (PMID 26024304, 2015). "Knockout of either of them causes insulin resistance, whereas only IRS-2-knockout results in diabetes." (PMID 25580119, 2014). "The aim of the study was to investigate if IRS-1 Gly972Arg and IRS-2 Gly1057Asp influence insulin resistance and are associated with risk of PCOS in the Chinese PCOS patients and controls from Taiwan." (PMID 25310961, 2014). "Irs2-deficient mice develop diabetes owing to reduced beta cell mass and peripheral insulin resistance." (PMID 23741292, 2013). "A recent study revealed that systemic insulin resistance and subclinical atherosclerosis are associated with decreased insulin receptor substrate 2 and tissue inhibitor of metalloproteinase-3 expression in circulating monocytes." (PMID 24373412, 2013). "Mouse genetic data have shown that deletion of Irs1 and Irs2 genes in the mouse liver (IrsLDKO) causes severe insulin resistance and early onset of diabetes." (PMID 23940800, 2013). "The ZnT7 null mice were susceptible to diet-induced glucose intolerance and insulin resistance and this was associated with a decrease in the expression of the insulin receptor, insulin receptor substrate 2 and Akt1." (PMID 24265765, 2013). "In the Irs2-deficient mouse model, diabetes develops due to reduced beta cell mass and insulin resistance, and most males die by 16 weeks of age due to a severe catabolic state as evidenced by weight loss, ketonuria and polydypsia." (PMID 23741292, 2013). "Although IrsLDKO mice are only deficient in hepatic Irs1 and Irs2, they manifest systemic insulin resistance as well, which is indicated by decreased phosphorylation of Akt and Erk in the skeletal muscle." (PMID 23940800, 2013). "Loss of Irs2 causes diabetes in mice due to beta cell insufficiency and peripheral insulin resistance." (PMID 23741292, 2013). "Mice with full deletion of Irs2 show peripheral insulin resistance and islet cell loss that progress to diabetes." (PMID 22563476, 2012). "In 190 of the 454 total study subjects, we investigated the relationship between Gly1057Asp polymorphism in IRS-2 and insulin resistance, which was evaluated using the HOMA-IR index." (PMID 23216712, 2012). "When we investigated the relationship between Gly1057Asp polymorphism in IRS-2 and insulin resistance we studied only 190 of the total 454 patients." (PMID 23216712, 2012). "Insulin resistance in human metabolic syndrome patients is associated with decreased expression of the insulin receptor substrate-2- (Irs2-) AKT2 axis in mononuclear leukocytes (MLs)." (PMID 22347652, 2011). "Variants currently identified in genes encoding the IRS-1, IRS-2 and GLUTs proteins correlate with insulin resistance." (PMID 18570670, 2008).
Insulin resistance (continued). "In certain disease states, such as polycystic ovary syndrome (PCOS), the common GlyAsp polymorphism in IRS2 may be associated with the insulin resistance observed in patients with PCOS." (PMID 40747301, 2025). "Inhibition of insulin receptor kinase by protein kinase C activation induced by diacylglycerol and reduced expression of insulin receptor substrate 2 (IRS2), a signaling molecule downstream of insulin receptor kinase, could cause hepatic insulin resistance." (PMID 38256005, 2024). "IRS2 variants are associated with glucose intolerance in women experiencing obesity, with diabetes-related traits in people of Pima ancestry, and with insulin resistance in people of Japanese ancestry with obesity." (PMID 37712417, 2023). "Polymorphisms among genes (IRS1 and IRS2) have been found for insulin resistance." (PMID 35327342, 2022). "Moreover, the common polymorphism Gly1057Asp in the IRS2 gene has also been reported to influence the susceptibility to insulin resistance and T2DM in polycystic ovary syndrome women." (PMID 34449768, 2021). "All these data lend support to the notion that differential hepatic distribution of Irs1/Irs2 could be one of the mechanisms underlying the selective insulin resistance observed in MAFLD." (PMID 33923817, 2021). "We hypothesized that the IRS1 (Gly972Arg) and IRS2 (Gly1057Asp) genes may influence insulin resistance and are associated with risk of OSA and NAFLD in overweight non-diabetic Asian Indians." (PMID 34449768, 2021). "The adverse effect of TRPC6 knockout on glomerular pathology was associated with insulin resistance that was, at least partially, due to decreased expression of the calcineurin-responsive gene IRS2 (insulin receptor substrate 2), which plays a critical role in insulin signaling." (PMID 31877991, 2019). "This indicated that IRS1 and IRS2 were related to HCV-associated insulin resistance." (PMID 29285303, 2017). "Moreover, vascular insulin resistance caused by the deletion of endothelial-specific insulin receptor substrate 2 (IRS-2) has been found to be sufficient for the development of systemic glucose intolerance." (PMID 27128347, 2016). "However, the IRS-2 requires a higher insulin concentration for activation, the hallmark of insulin resistance." (PMID 25310961, 2014). "Moreover, the most common variant Gly1057Asp (rs1805097) in the IRS-2 gene has also been reported to influence the susceptibility to insulin resistance and type 2 diabetes in PCOS women." (PMID 25310961, 2014). "The increased basal phosphorylation of AKT and ERK, observed in testes of Irs2-deficient mice, has been previously reported in skeletal muscle and liver in the Irs2-deficient mouse model and may represent an important component of insulin resistance." (PMID 23741292, 2013). "Thus, further investigation is needed to clarify the relationship between Gly1057Asp polymorphism in IRS-2 and insulin resistance." (PMID 23216712, 2012). "Because the Asp allele at codon 1057 in IRS-2 seems to be associated with the low risk of insulin resistance and DM, we hypothesize that the Asp allele plays a protective role for CAD." (PMID 23216712, 2012). "Insulin resistance (IR) in patients with metabolic syndrome (MetS), who are at high cardiovascular risk, is associated with impaired insulin signaling via the insulin receptor substrate-2- (Irs2-) AKT2 pathway in mononuclear leukocytes (MLs)." (PMID 22347652, 2011). "Furthermore, IRS-2 signaling was repressed in hepatic insulin resistance by short-term feeding of FFAs, which caused a 3-fold increase in triglycerides and acyl-CoAs." (PMID 20300478, 2009). "Interestingly, while systemic heterozygous IRS-2 deficiency improved insulin sensitivity, brain-specific IRS-2 knock out led to insulin resistance." (PMID 19412415, 2007).